ZNF354C (zinc finger protein 354C)
Description:
Transcriptional repressor that inhibits endothelial angiogenic sprouting. Suppresses osteogenic effects of RUNX2 and may be involved in osteoblastic differentiation (By similarity). Plays a role in postnatal myogenesis, may be involved in the regulation of satellite cells self-renewal (By similarity).
Synonyms: KID3
Tractability: PROTAC: UniProt records ubiquitination sites on it; ubiquitination databases record sites on it.
Gene: Protein-coding gene on chromosome 5 (179,060,361 to 179,083,977, forward strand). Ensembl gene ENSG00000177932.
Subcellular location: Nucleus; Nucleus membrane; Cytoplasm
Subcellular location (Human Protein Atlas): Nucleoplasm
Pathways (Reactome):
Gene expression (Transcription): Generic Transcription Pathway
Gene Ontology:
Molecular function: DNA-binding transcription repressor activity, RNA polymerase II-specific; protein binding; DNA-binding transcription factor activity, RNA polymerase II-specific; RNA polymerase II cis-regulatory region sequence-specific DNA binding
Biological process: negative regulation of sprouting angiogenesis; regulation of transcription by RNA polymerase II; negative regulation of transcription by RNA polymerase II; regulation of DNA-templated transcription
Cellular component: cytoplasm; nuclear membrane; nucleoplasm; nucleus
Genetic constraint (gnomAD): Loss-of-function variants: 7 observed, 14.26 expected, observed/expected ratio (o/e) 0.49, 90% interval 0.28 to 0.92. The upper end of that interval is the gene's LOEUF score, 0.92, which puts it in group 3 of 6, group 1 being the genes least tolerant of losing a copy. Missense variants: 607 observed, 690.94 expected, observed/expected ratio (o/e) 0.88, 90% interval 0.82 to 0.94. Synonymous variants: 201 observed, 237.15 expected, observed/expected ratio (o/e) 0.85, 90% interval 0.75 to 0.95.
Homologues: Orthologues: chimpanzee ZNF354C (99% identical), macaque ZNF354C (95% identical), rabbit ZNF354C (78% identical), pig ZNF354C (77% identical), mouse Zfp354c (75% identical), rat Zfp354c (75% identical), guinea pig ZNF354C (67% identical). Paralogues in human: ZNF879 (48% identical), ZNF7 (47% identical), ZNF28 (46% identical), ZNF595 (46% identical), ZNF728 (46% identical), ZNF568 (46% identical), ZNF85 (46% identical), ZNF724 (45% identical), ZNF708 (45% identical), ZNF658 (45% identical), ZNF726 (45% identical), ZNF429 (45% identical), and 164 more.
Diseases named in the same sentence as ZNF354C in open-access papers:
ZNF354C is named in the same sentence as 10 diseases in open-access papers, as found by Europe PMC text mining. Sharing a sentence is not in itself a finding about the gene and the disease. The quoted sentences say what the papers report.
COVID-19 (2 papers, 2021 to 2025). A disease caused by infection with severe acute respiratory syndrome coronavirus 2. "Ankryin B, which aligns to SP597-606, has been reported to be transcribed in lungs of COVID-19 patients, where it is not usually expressed, and ZNF354C, aligning to NP361-390, is a transcription factor which interacts with genes that are differentially expressed in SARS-CoV-2 infected patients." (PMID 36303764, 2021).
depression (1 paper, 2016). "In conclusion, we identified rs1863918 as significantly associated with IFN-induced depression, and revealed that the candidate gene ZNF354C is highly expressed in the hippocampus of mice." (PMID 27723809, 2016). "Taken together, when rs1863918 SNP is T allele, it is assumed that ZBTB3 plays a direct role in these processes by binding to the target region or has an indirect role by upregulating ZNF354C expression in the hippocampus as the onset mechanism of depression." (PMID 27723809, 2016). "Because the expression level of ZNF354C was high in the hippocampus, it is suggested ZNF354C might be involved in the onset of depression." (PMID 27723809, 2016).
ovarian carcinoma (1 paper, 2021). A malignant neoplasm originating from the surface ovarian epithelium. "ZNF354C and TBX15 have been reported to be related to the occurrence of various cancers, including breast and ovarian cancer." (PMID 34824921, 2021).
cancer (2 papers, 2015 to 2021). A tumor composed of atypical neoplastic, often pleomorphic cells that invade other tissues. "Seven genes are hypermethylated in ten cancer sites: six encoding zinc finger transcription factors (ZNF135, ZNF354C, ZNF415, ZNF542, ZNF671, ZSCAN18) and one encoding a transmembrane protein (TMEM25)." (PMID 25631659, 2015).
tumour (1 paper, 2020). "Given that ZNF354C has so far only been studied in bone and tumour, its function was determined in endothelial cells." (PMID 33154469, 2020).
ZNF354C also shares sentences with these, for which no sentence is quoted: cardiac hypertrophy (1 paper); Chronic Hepatitis C (1); esophagus neoplasms (1); Ischaemia (1); Urinary incontinence (1).